ENSG00000280371 ( gene)
Diseases named in the same sentence as ENSG00000280371 in open-access papers (continued):
Sharing a sentence is not in itself a finding about the gene and the disease.
pancreatic cancer (8 papers, 2014 to 2025). "DNA cross‐link repair 1B (DCLRE1B), a 5′‐to‐3′ exonuclease, a DNA repair gene, is upregulated in pancreatic cancer, promotes the proliferation of pancreatic cancer cells, and is associated with poor prognosis." (PMID 40448344, 2025). "In conclusion, our present study demonstrated that FUT11 is a new hypoxia related gene, and is overexpressed in pancreatic cancer tissues and related to poor prognosis of pancreatic cancer patients." (PMID 34221996, 2021). "For example, miR-130a is upregulated in oral squamous cell carcinoma and suppresses expression of TSC1, a tumor suppressor gene, and an miR-301a inhibitor suppresses pancreatic tumor growth in a xenograft model." (PMID 34830336, 2021).
cervical cancer (7 papers, 2015 to 2024). A primary or metastatic malignant neoplasm involving the cervix. "ST20, also known as HCCS-1, exhibits downregulated expression in a variety of human malignancies, potentially fulfilling the role of a tumor suppressor gene by activating apoptotic signaling pathways, thereby restraining the progression of cervical cancer." (PMID 39309810, 2024). "It is well known miR-653-5p may target chromosome 11 open reading frame 30, and miR-653-5p acts as a tumor suppressor gene in cervical cancer." (PMID 34866540, 2021).
glioblastoma (7 papers, 2012 to 2024). The most malignant astrocytic tumor (WHO grade IV). "Remarkably, ERRFI1 is lauded as a tumor suppressor gene of glioblastomas, whose high expression can diminish the migration of glioblastoma cells." (PMID 33117083, 2020). "Here, we propose that JMJD3 acts as a tumor suppressor gene in glioblastoma multiforme." (PMID 23236496, 2012). "QKI and PARK2 are located within the same minimal common region on chromosome 6q26-27; PARK2 is a tumor suppressor gene in GBM (glioblastoma), and has an additive effect with QKI in tumor suppression." (PMID 39479357, 2024). "It is not clear why iron-regulating gene function fails to differentiate long- and short-term survivors in glioblastoma multiforme, especially considering the evidence that polymorphisms in a single iron-regulatory gene, HFE, may decrease survival in GBM." (PMID 27898674, 2016).
esophageal cancer (6 papers, 2013 to 2026). A primary or metastatic malignant neoplasm involving the esophagus. "In summary, miR-139-5p was identified as a tumor suppressor gene associated with the risk for esophageal cancer, and a novel mechanism of regulation of NR5A2 protein by miR-139-5p was reported." (PMID 24204738, 2013). "The results suggest that miR-139-5p functions as a tumor-suppressor gene involved in esophageal cancer development." (PMID 24204738, 2013). "Many studies suggested that SPINK7 may function as a tumor suppressor gene regulating the protease cascades during carcinogenesis and invasion of esophageal cancer." (PMID 29301256, 2018).
Obesity (6 papers, 2015 to 2024). Accumulation of substantial excess body fat. "We report that deletion of the innate immunity antibacterial gene Nod2 abolishes this resistance, as Nod2−/− BALB/c mice developed HFD-dependent obesity and hallmark features of metabolic syndrome." (PMID 28373658, 2017). "Previously, it was shown that whole-body Ahr knockout mice on HFD have increased transcript levels of the thermogenic uncoupling gene Ucp1 in BAT as compared wild type mice, potentially explaining how Ahr knockout could protect against HFD induced obesity." (PMID 32730300, 2020).
lung adenocarcinoma (5 papers, 2022 to 2025). A carcinoma that arises from the lung and is characterized by the presence of malignant glandular epithelial cells. "Glucosamine 6-phosphate N-acetyltransferase (GNPNAT1), which serves as a critical enzyme in hexosamine biosynthetic pathway (HBP), has been identified as a metastasis-associated gene and is upregulated in lung adenocarcinoma (LUAD)." (PMID 39062049, 2024). "However, the expression of GPM6A decreases in lung adenocarcinoma, liver cancer, thyroid cancer, and so forth as the tumor progresses, indicating that it may be a tumor suppressor gene." (PMID 39957375, 2025).
thyroid cancer (5 papers, 2020 to 2025). "Previous studies have elucidated the dual role of UBE2C in thyroid cancer (THCA) as both a tumor suppressor gene and an oncogene." (PMID 38577722, 2024).
autism (4 papers, 2009 to 2024). Persistent deficits in social interaction and communication and interaction as well as a markedly restricted repertoire of activity and interest as well as repetitive patterns of behavior. "We found a significant association between autism and a coding variant in the seizure-related gene SEZ6L2 (12/1106 autism vs. 3/1161 controls; p = 0.018)." (PMID 19242545, 2009). "Regarding IFI16, an anti-inflammatory gene, we found a highly significantly reduced expression in the NSCs (75%) but a significantly increased expression in the astrocytes (>45%) of patients with autism vs. controls." (PMID 38994948, 2024). "This is consistent with the traditional view of Top2a’s role as a “housekeeping” gene with no known selectivity for autism risk genes, although a Top2a ChIP-seq experiment in neurons or developing brains of zebrafish will be needed to confirm this finding." (PMID 36417527, 2022). "Human sex differences in autophagy are prominent in the brain and other tissues, with sex-differential effects from genetic variation also found in the autophagy-regulating gene ADNP (Activity-Dependent Neuroprotective Protein), which, like AMBRA1, affects autism and schizophrenia risk and traits." (PMID 31687209, 2019).
brain tumors (4 papers, 2010 to 2018). "Based on previous reports, miR-34a is considered a putative tumor suppressor gene in various types of cancers including brain tumors." (PMID 25551588, 2014). "In addition, CDKN3 has been proposed to be a tumor suppressor gene of brain tumors and of mitosis control." (PMID 26372210, 2015). "There was also a tendency for association between the 2251G minor allele of the nucleotide excision DNA repair gene XPD in both homo- and heterozygous forms and an increased chance of developing a brain tumor ( p = 0.084, OR = 1.48, 95% confidence interval 0.97–2.27)." (PMID 22649665, 2010). "In the context of brain tumors, expression of BECN1, a specific autophagy gene, is lower in GBMs compared to lower grade astrocytomas and normal brain tissues." (PMID 29692710, 2018).
cholangiocarcinoma (4 papers, 2020 to 2025). A carcinoma that arises from the intrahepatic biliary tree (intrahepatic cholangiocarcinoma) or from the junction, or adjacent to the junction, of the right and left hepatic ducts (hilar cholangiocarcinoma). "ARID1A, a chromatin remodeling gene, is implicated in multiple malignancies including HCC and cholangiocarcinoma." (PMID 41146957, 2025). "In this report, we mined the published cholangiocarcinoma transcriptome data set (GSE26566), compared it with the ubiquitination-associated gene (GO:0016567), and identified that UBE2C was highly expressed in cholangiocarcinoma tumor tissue." (PMID 38102624, 2023). "Reviewing the literatures, we found that APOB played a role as an oncogene in many tumors, but not as a potential tumor suppressor gene in cholangiocarcinoma as we found." (PMID 33954113, 2021).
colorectal tumor (4 papers, 2016 to 2022). "This association between rs2282151 and CRC is probably mediated by the expression of the inflammatory-related gene HSP90AB1, which is upregulated in colorectal tumor tissues." (PMID 27756247, 2016).
Lynch syndrome (4 papers, 2009 to 2025). An autosomal dominant hereditary neoplastic syndrome characterized by the development of colorectal carcinoma and a high risk of developing endometrial carcinoma, gastric carcinoma, ovarian carcinoma, renal pelvis carcinoma, and small intestinal carcinoma. "MSH6, a key DNA mismatch repair gene, is highly expressed in PGCs,31,41 and its mutations are linked to Lynch syndrome." (PMID 39999848, 2025). "It has been proposed that one additional mismatch repair gene, mutL homolog 3 (MLH3), also plays a role in Lynch syndrome predisposition, but the clinical significance of mutations in this gene is less clear." (PMID 19466295, 2009).
neuroblastoma (4 papers, 2015 to 2025). Neuroblastoma (NB) is the most common solid, extracranial childhood tumor. "Exostosin-like glycosyltransferase 1 (EXTL1), a member of the EXT family of tumor suppressor genes, was identified as a candidate neuroblastoma tumor-suppressor gene." (PMID 40660393, 2025). "Here we also evaluated whether CASZ1a interacts with another NuRD subunit CHD5, which is a neuroblastoma tumor suppressor gene." (PMID 26296975, 2015).
squamous cell carcinoma (4 papers, 2008 to 2024). A carcinoma arising from squamous epithelial cells. "The role of miR124 has been resembled to a tumor suppressor gene which is mediated by inhibition of SPHK1 gene in squamous cell carcinoma." (PMID 39315290, 2024). "In summary, the action of NOTCH1 in the development of squamous cell carcinomas, its role as both a tumor suppressor gene and as a protooncogene, is not yet fully understood." (PMID 37008245, 2023). "VILIP-1, a member of the neuronal Ca++ sensor protein family, acts as a tumor suppressor gene in an experimental animal model by inhibiting cell proliferation, adhesion and invasiveness of squamous cell carcinoma cells." (PMID 18301774, 2008).
bladder cancer (3 papers, 2009 to 2015). "Rho GDP dissociation inhibitor 2 (RhoGDI2) has recently been identified as a metastasis suppressor gene in models of bladder cancer." (PMID 24137348, 2013). "In breast, lung, prostate and bladder cancer, WIF1 expression was found to be frequently downregulated, suggesting it might represent a tumor suppressor gene." (PMID 19570204, 2009).
bladder tumor (3 papers, 2012 to 2020). "Approximately 76% of all primary bladder tumors display mutations in at least one chromatin regulatory gene." (PMID 31627336, 2019). "APOE has been shown to interact with the transitional epithelial response gene (TERE1), a tumor suppressor gene, in bladder tumor cells, resulting in increased cell turnover and resistance to apoptosis." (PMID 23094052, 2012). "In conclusion, our study demonstrated for the first time that TET1 may function as a tumor suppressor gene in UBC and AJAP1 plays a crucial role in TET1 suppression of bladder tumor growth through modulation of the Wnt/β-catenin signaling, affecting its downstream target genes." (PMID 32528872, 2020).
endometriosis (3 papers, 2017 to 2025). The growth of functional endometrial tissue in anatomic sites outside the uterine body. "DDR2 is a key hypoxia‐related gene in endometriosis and a promising diagnostic and therapeutic biomarker." (PMID 41424583, 2025).
kidney cancer (3 papers, 2013 to 2020). Primary or metastatic malignant neoplasm involving the kidney. "Our study indicates that TRIM33 plays a role as a tumor suppressor gene in ccRCC and may become a potential target and prognostic marker for kidney cancer treatment in the future." (PMID 32908919, 2020).
liver cancer (3 papers, 2005 to 2025). An epithelial or non-epithelial malignant neoplasm that arises from the liver. "Whereas opposite evidence of YTHDC2 as a tumor suppressor gene is also reported in liver cancer, covering the underneath mechanisms a heterogeneous veil." (PMID 34497675, 2021).
oral squamous cell carcinoma (3 papers, 2021 to 2022). "Cisplatin-activated autophagy promotes the expression of circ-PKD2, which plays a role as a tumor suppressor gene in the proliferation, migration, and invasion in oral squamous cell carcinoma (OSCC)." (PMID 35220397, 2022).
renal carcinoma (3 papers, 2022). A carcinoma arising from the epithelium of the renal parenchyma or the renal pelvis. "Importantly, the overexpression of KCNJ15 was shown to significantly inhibit the proliferation, migration, and colony formation of renal cancer cells, arrest the cell cycle and induce cancer cell apoptosis, which may be a tumor suppressor gene in renal cancer." (PMID 36389709, 2022). "We infected the human renal carcinoma cell line iSLK with a modified version of the BAC16 KSHV genome containing a far-red fluorescent protein (mIFP2) driven by the promoter of the viral late gene K8.1 as well as a constitutive EGFP." (PMID 35041709, 2022).
renal cell carcinoma (3 papers, 2019 to 2022). "In addition, IDUA is a novel glycolysis-related gene that is associated with the immune microenvironment in renal cell carcinoma." (PMID 35945500, 2022).
schizophrenia (3 papers, 2017 to 2019). A major psychotic disorder characterized by abnormalities in the perception or expression of reality. "Human studies of schizophrenia are now reporting a previously unidentified genetic convergence on postsynaptic signaling complexes such as the activity-regulated cytoskeletal-associated (Arc) gene." (PMID 28979198, 2017). "In addition, mRNA levels of myelin-associated oligodendrocyte basic protein (MOBP), an oligodendrocyte-associated gene, are increased in Pfc white matter in schizophrenia patients." (PMID 29163023, 2017).
virus infection (3 papers, 2017 to 2025). "Additionally, the expression of the JA-regulated defense gene PI-II in tomato plants was repressed by virus infection." (PMID 28373670, 2017).
astrocytomas (2 papers, 2018 to 2019). "In contrast, in astrocytomas IDH-wildtype the deletion of PTEN is a factor of poor prognosis, as expected, since this is a tumor suppressor gene." (PMID 31623593, 2019).
Bloom syndrome (2 papers, 2013 to 2022). Bloom syndrome (BSyn) is a rare chromosomal breakage syndrome characterized by a marked genetic instability associated with pre- and postnatal growth retardation, facial sun-sensitive telangiectatic erythema, increased susceptibility to infections, and predisposition to cancer. "There are five members of RecQ, which are RECQL (also called RECQL1), BLM (Bloom’s syndrome gene), WRN (Werner’s syndrome gene), RECQL4, and RECQL5 with unique biochemical functions." (PMID 35267530, 2022).
chronic myelogenous leukemia (2 papers, 2021 to 2024). "Although little is known about the function of PRDM12 in oncogenesis, previous studies showed that PRDM12 might act as a tumor suppressor gene in human chronic myeloid leukemia (CML)." (PMID 34769459, 2021).
clear cell renal cell carcinoma (2 papers, 2021 to 2022). "MTUS1, a tumour-suppressor gene encoding angiotensin-II type 2 receptor-interacting proteins, is downregulated in clear cell renal cell carcinoma." (PMID 34980126, 2022). "Previous studies have shown that is an innate immunity gene and involved in the development of eczema, clear cell renal cell carcinoma, meningioma, and childhood leukemia." (PMID 33579299, 2021).
colitis (2 papers, 2024 to 2025). Inflammation of the colon. "At the same time, the antimicrobial peptide activates the expression of the wnt frizzled gene in the wnt pathway, promotes the generation of intestinal stem cells, promotes the differentiation and repair of intestinal epithelial cells, and prevents colitis." (PMID 38254536, 2024).
depression (2 papers, 2025). "Over-expression of NEGR1, a synapse-adhesion gene highlighted by psychiatric GWAS, induces depression-like behaviour and impairs myelination; knocking it down rescues stress-induced anhedonia, revealing a fresh therapeutic target for synaptic repair." (PMID 41373485, 2025).
Fanconi anemia (2 papers, 2021). Fanconi anemia (FA) is a hereditary DNA repair disorder characterized by progressive pancytopenia with bone marrow failure, variable congenital malformations and predisposition to develop hematological or solid tumors. "Other candidate genes with known roles for CSAs included GTF2H (general transcription factor IIH subunits 4 and 5), Fanconi anemia pathway genes, and PMS2, a mismatch repair gene." (PMID 34220964, 2021).
Intellectual disability (2 papers, 2022 to 2024). "FXR1 on the other hand is an RNA-binding protein and ortholog of the fragile X and mental retardation gene FMR1." (PMID 35666183, 2022).
muscular dystrophy (2 papers, 2013 to 2021). Muscular dystrophy (MD) refers to a group of more than 30 genetic diseases characterized by progressive weakness and degeneration of the skeletal muscles that control movement. "Expression of the Duchenne muscular dystrophy gene (Dmd) was detectable only in MEFs, which can be induced to differentiate into myotube-like cells under different conditions." (PMID 23451074, 2013).
non-melanoma skin carcinoma (2 papers, 2015 to 2024). "We speculate that lincRNA-p21 may function as a tumor suppressor gene in UVB-induced non-melanoma skin cancer where the loss of lincRNA-p21 expression results in the evasion of apoptosis." (PMID 25789975, 2015).
Parkinson disease (2 papers, 2013 to 2022). A progressive degenerative disorder of the central nervous system characterized by loss of dopamine producing neurons in the substantia nigra and the presence of Lewy bodies in the substantia nigra and locus coeruleus. "Remarkably, djr-1.1 and djr-1.2 are homologs of the Parkinson’s disease-associated human gene DJ-1, also known as PARK7." (PMID 24324795, 2013).
sarcoma (2 papers, 2015 to 2023). A usually aggressive malignant neoplasm of the soft tissue or bone. "To further test the functional significance of miR-16 as a metastasis suppressor gene, we used a loss-of-function approach in primary sarcomas." (PMID 26044957, 2015).
Stroke (2 papers, 2017 to 2024). Sudden impairment of blood flow to a part of the brain due to occlusion or rupture of an artery to the brain. "The concentration of related proteins in the serum of stroke patients was determined by ELISA, and the patients were divided into groups to evaluate the effect of the ribosome biogenesis gene on patients." (PMID 39290696, 2024).
T cell lymphomas (2 papers, 2016 to 2023). "Thus, consistent with heterozygous mutations of Dnmt3a found in human T cell malignancies, Dnmt3a is a haploinsufficient tumor suppressor gene in the prevention of mouse mature CD8+CD4- T cell lymphomas." (PMID 27690235, 2016). "Kcnj16 is frequently mutated in T-cell lymphoma in mice lacking the DNA mismatch repair gene Mlh1, but its function in T-cell lymphoma remains unclear." (PMID 36923292, 2023).
abscess (1 paper, 2022). An inflammatory process characterized by the accumulation of pus within a newly formed tissue cavity which is the result of a bacterial, fungal, or parasitic infection or the presence of a foreign body. "Gene sdrD (serine–aspartate repeat protein D) is member of the MSCRAMMs (microbial surface components recognizing adhesive matrix molecules), promotes the adherence of S. aureus to nasal epithelial cells, human keratinocytes, and contributes to abscess formation." (PMID 36009880, 2022).
adenoma (1 paper, 2023). A neoplasm arising from the epithelium. "The genes CA2, CA7, and ITM2C collectively play critical roles in CRC progression, with CA2 influencing adenoma characteristics and cell proliferation, CA7 acting as a tumor suppressor gene, and ITM2C likely sharing similar tumor-suppressive properties with its family member ITM2A." (PMID 37895185, 2023).